AKR7A3 (aldo-keto reductase family 7 member A3)
Description:
Catalyzes the NADPH-dependent reduction of various carbonyl-containing compounds, including aldehydes, ketones, and toxic products from cellular metabolism or environmental exposure. Can reduce the dialdehyde form of aflatoxin B1 (AFB1) into alcohol derivatives, via monoaldehydes intermediates. Can reduce the dialdehyde form of aflatoxin B1 (AFB1) into alcohol derivatives, via monoaldehydes intermediates, thus preventing the formation of protein adducts that contribute to AFB1-induced toxicity.
Synonyms: AFAR2
Tractability: Small molecule: a structure with a bound ligand is known; it has a high-quality binding pocket. PROTAC: its protein half-life has been measured.
Gene: Protein-coding gene on chromosome 1 (19,282,496 to 19,288,823, reverse strand). Ensembl gene ENSG00000162482.
Subcellular location: Cytoplasm
Subcellular location (Human Protein Atlas): Cytosol; Golgi apparatus
Pathways (Reactome):
Metabolism: Aflatoxin activation and detoxification
Gene Ontology:
Molecular function: alcohol dehydrogenase (NADP+) activity; identical protein binding; protein binding; electron transfer activity; NADP+ binding
Biological process: aflatoxin catabolic process; aldehyde metabolic process
Cellular component: cytosol; extracellular exosome; cytoplasm; Golgi apparatus
Genetic constraint (gnomAD): Loss-of-function variants: 37 observed, 34.56 expected, observed/expected ratio (o/e) 1.07, 90% interval 0.82 to 1.41. The upper end of that interval is the gene's LOEUF score, 1.41, which puts it in group 5 of 6, group 1 being the genes least tolerant of losing a copy. Missense variants: 382 observed, 429.81 expected, observed/expected ratio (o/e) 0.89, 90% interval 0.82 to 0.97. Synonymous variants: 171 observed, 174.54 expected, observed/expected ratio (o/e) 0.98, 90% interval 0.86 to 1.11.
Homologues: Orthologues: chimpanzee AKR7A3 (97% identical), macaque AKR7A3 (94% identical), rat Akr7a3 (80% identical), zebrafish akr1a1a (23% identical), Drosophila melanogaster CG6083 (21% identical), tropical clawed frog XB5731323 (21% identical), zebrafish zgc:110366 (21% identical), Caenorhabditis elegans C01G5.5 (21% identical), zebrafish zgc:101765 (21% identical), Caenorhabditis elegans C07D8.6 (20% identical), Caenorhabditis elegans F53F1.3 (20% identical), Caenorhabditis elegans Y39G8B.1 (20% identical), and 11 more. Paralogues in human: AKR7L (92% identical), AKR7A2 (87% identical), AKR1C2 (24% identical), KCNAB1 (24% identical), AKR1C1 (24% identical), AKR1C3 (24% identical), AKR1A1 (24% identical), AKR1B10 (24% identical), AKR1C4 (24% identical), AKR1D1 (24% identical), KCNAB2 (23% identical), KCNAB3 (23% identical), and 4 more.
Diseases named in the same sentence as AKR7A3 in open-access papers:
AKR7A3 is named in the same sentence as 10 diseases in open-access papers, as found by Europe PMC text mining. Sharing a sentence is not in itself a finding about the gene and the disease. The quoted sentences say what the papers report.
hepatocellular carcinoma (3 papers, 2014 to 2023). A malignant tumor that arises from hepatocytes. "Here, we reported that AKR7A3 acts as a potent tumor suppressor in hepatocellular carcinoma." (PMID 29137357, 2017).
liver cancer (3 papers, 2014 to 2023). An epithelial or non-epithelial malignant neoplasm that arises from the liver. "In order to understand the underlying mechanisms of AKR7A3 tumor suppressive effects, the activity of certain important signaling pathways in liver cancer development, including MAPK, c-Jun and NF-κB, were detected by western blot." (PMID 29137357, 2017).
breast carcinoma (2 papers, 2014 to 2017). "Associations of AKR1C2, AKR7A3, and CBR1 with prognosis of breast carcinoma patients revealed by this study should be further followed in independent validation and functional studies." (PMID 25526449, 2014). "AKR7A3 protein expression was found in breast tumors for the first time and its high correlation with mRNA levels (P < 0.001) demonstrates the biological relevance of AKR7A3 for breast carcinoma." (PMID 25526449, 2014). "Mechanisms of action of AKR1C2, AKR7A3, CYP2B6, CYP3A4, and CBR1 should continue to be further followed in breast carcinoma patients and models." (PMID 25526449, 2014). "As no other data about the role of AKR7A3 in the prognosis of breast carcinoma patients exist, validation of our findings will be subject of independent follow-up studies." (PMID 25526449, 2014).
fibrosis (1 paper, 2020). the formation of excess fibrous connective tissue in an organ or tissue in a reparative or reactive process. "The analysis of the nine genes, namely A2m, Akr7a3, Aqp7, Ca3, Cdc2a, Cdkn3, Cyp2c11, Ntf3, and Sds, revealed the association between NGHCs and chronic inflammatory liver conditions, including liver cirrhosis and fibrosis." (PMID 32560183, 2020).
multiple myeloma (1 paper, 2025). "Collectively, these findings suggest that UNC13B may regulate multiple oncogenic and apoptotic signaling pathways—such as those involving PINK1, CDK2, AKR7A3, and Bim—to promote cell survival and proliferation in multiple myeloma." (PMID 41007649, 2025).
tumor (5 papers, 2014 to 2025). "Representative images of six paired HCC samples with AKR7A3 down-regulation showed higher prominence of methylated allele in tumor samples and unmethylated allele in non-tumor samples." (PMID 29137357, 2017). "Functional assays on both AKR7A3 overexpressed and knockdown cells, including foci formation, colony formation in soft agar, migration, invasion and tumor formation in nude mice, demonstrated the strong tumor suppressive functions of AKR7A3." (PMID 29137357, 2017). "In order to study the tumor suppressive functions of AKR7A3 in HCC, the CDS sequence of this gene was cloned into a lentiviral vector." (PMID 29137357, 2017). "Among these 55 samples, 30 showed AKR7A3 down-regulation and 13 of them were detected with allele loss, demonstrated by LOH of tumor DNA samples." (PMID 29137357, 2017). "Here, we reported that AKR7A3 is frequently down-regulated in HCC tissues compared to adjacent non-tumor tissues." (PMID 29137357, 2017). "In light of the confirmation of the tumor suppressive abilities of AKR7A3, the downstream signaling pathways were studied." (PMID 29137357, 2017). "In vivo tumor formation experiments in nude mice also demonstrated the inhibition of tumor formation by AKR7A3 overexpression." (PMID 29137357, 2017). "In vitro functional studies, including foci formation, colony formation in soft agar, migration and invasion, revealed strong tumor suppressive functions of AKR7A3." (PMID 29137357, 2017). "We further validated AKR7A3 functions through in vivo tumor formation assay in nude mice." (PMID 29137357, 2017). "Our data showed that AKR7A3 potently inactivates ERK phosphorylation, which could in part explain the strong tumor suppressive effects of AKR7A3." (PMID 29137357, 2017). "Protein levels of AKR1C1, AKR7A3, and CBR1 significantly correlated with the respective transcript levels assessed by qPCR in the same tumor samples (Spearman ρ = 0.47, P = 0.003, Spearman ρ = 0.61, P < 0.001, and Spearman ρ = 0.44, P = 0.007, respectively)." (PMID 25526449, 2014). "Expression of AKR1C1, AKR1C2, AKR7A3, CYP3A4, and CBR1 was assessed by immunoblotting in protein lysates from tumor tissue samples of the independent pretreatment set of patients." (PMID 25526449, 2014). "Mechanistically, UNC13B may exert tumor-promoting effects by modulating key regulatory proteins, including PINK1, CDK2, AKR7A3, and Bim." (PMID 41007649, 2025). "Only AKR7A3 and SDCBP2 were consistently upregulated strictly in tumor cells." (PMID 35995947, 2022). "In paired HCC samples (274N and 274T), where AKR7A3 was down-regulated by more than 100 folds in tumor tissue, the promotor region of AKR7A3 was found to be hypermethylated in tumor tissue, as compared to adjacent non-tumor tissue." (PMID 29137357, 2017). "Collectively, our data demonstrated frequent down-regulation and clinical significance of AKR7A3 in HCC, as well as its strong tumor suppressive functions and inhibition of chemoresistance, which could be attributed to the attenuation of ERK, c-Jun and NF-κB signaling pathways." (PMID 29137357, 2017). "Additionally, in GC patients, AKR7A3 expression did not correlate with tumor stage." (PMID 36827074, 2023).
AKR7A3 also shares sentences with these, for which no sentence is quoted: cancer (4 papers); breast tumors (1); liver cirrhosis (1); Niemann-Pick disease, type C2 (1).